MCL1 (MCL1 apoptosis regulator, BCL2 family member)
Diseases named in the same sentence as MCL1 in open-access papers (continued):
Sharing a sentence is not in itself a finding about the gene and the disease.
lymph node metastasis (4 papers, 2017 to 2021). "A clinicopathologic association study in patients with GBC demonstrated that high expression of pSTAT3, CEBPD, and MCL1 was significantly associated with advanced clinical stages, tumor grades, and lymph node metastasis." (PMID 34156978, 2021). "SRSF5 expression is increased, associated with lymph node metastasis, and involved in the production of the anti-apoptotic form of Mcl-1 in breast cancers." (PMID 28536481, 2017). "In patients with lymph node metastasis (n=127), high MCL1 gain tended to associate with poorer DFS (P=0.098) and OS (P=0.133)." (PMID 29152113, 2017). "In patients with lymph node metastasis and with disease free survival time greater than or equal to 29 months (n=36), high MCL1 gain tended to associate with poorer DFS (P=0.007) and OS (P=0.029)." (PMID 29152113, 2017). "Reversely, among patients with lymph node metastasis or stage III-IVa patients, high MCL1 gain was associated with poorer DFS (P=0.007 or 0.021) and OS (P=0.029 or 0.068) after disease free survival time was more than or equal to 29 months." (PMID 29152113, 2017). "In this study, we report for the first time that high MCL1 gain was delayed bidirectional prognostic factor, and its prognostic significance was different in patients with different status of lymph node metastasis." (PMID 29152113, 2017). "High MCL1 gain was associated with better survival in patients without lymph node metastasis 12 months later, and poorer survival in patients with lymph node metastasis 29 months later." (PMID 29152113, 2017). "In patients without lymph node metastasis and with disease free survival time greater than or equal to 12 months (n=120), high MCL1 gain was associated with better DFS (P=0.009) and OS (P=0.014)." (PMID 29152113, 2017). "Interestingly, among patients without lymph node metastasis or stage I-II patients, high MCL1 gain was associated with better DFS (P=0.009 or 0.046) and OS (P=0.014 or 0.069) after disease free survival time was more than or equal to 12 months." (PMID 29152113, 2017). "However, in patients without lymph node metastasis (n=135), high MCL1 gain tended to associate with better DFS (P=0.090) and OS (P=0.081)." (PMID 29152113, 2017). "In conclusion, we observed that high MCL1 gain was poorer prognostic factor for DFS and OS in later stage of ESCC patients (with lymph node metastasis or stage III-IVa) 29 months later." (PMID 29152113, 2017). "Sex, age, grade, invasive depth, vessel involvement, nerve involvement, lymph node metastasis, tumor site, smoking and clinical stage were not statistically correlated with high MCL1 gain (P>0.05)." (PMID 29152113, 2017). "The expression of MCL1 was significantly down-regulated in CRC tissues with lymph node metastasis compared to those without lymph node metastasis, which is negatively related to the miR-125b expression level." (PMID 28881590, 2017). "To further investigate the relationship between MCL1 and CRC metastasis, we examined protein expression level of MCL1 in 16 CRC patients using Western Blot (8 cases with lymph node metastasis and 8 cases without lymph node metastasis)." (PMID 28881590, 2017). "High MCL1 copy number gain was found in 29.1% of 127 ESCC patients with lymph node metastasis and 29.6% of 135 ESCC patients without lymph node metastasis." (PMID 29152113, 2017).
myelodysplastic syndrome (4 papers, 2019 to 2023). A clonal hematopoietic disorder characterized by dysplasia and ineffective hematopoiesis in one or more of the hematopoietic cell lines. "The JAK2V617F mutation also enforced Mcl-1 transcription to sensitize myelodysplastic syndrome cell lines to apoptosis induced by a Bcl-xL/Bcl-2 inhibitor." (PMID 34773997, 2021). "Further, increased MCL-1 expression is associated with treatment resistance to myelodysplastic syndrome (MDS), which can evolve into AML." (PMID 31921615, 2019).
primary effusion lymphoma (4 papers, 2018 to 2023). A large B-cell lymphoma located in the body cavities, characterized by pleural, peritoneal, and pericardial fluid lymphomatous effusions and that is always associated with human herpes virus-8 (HHV-8). "Indeed, down-regulation of the expression of HSF1/Hsp70 by STAT3 inhibitor AG490 suppressed Mcl-1 and led to the induction of apoptosis and autophagy in primary effusion lymphoma cells." (PMID 29541415, 2018). "Interestingly, MCL-1 is highly expressed in tissues from patients with primary effusion lymphoma (PEL)." (PMID 33471866, 2021).
skin cancer (4 papers, 2014 to 2024). "As epidemiological studies also showed that the expression of anti-apoptotic BCL-2 can be higher than the expression of BCL-xL and MCL-1 in skin cancer cells, BH3 mimetic substances are in the focus of research and clinical trials." (PMID 37210688, 2023). "Our previous studies demonstrated that IMQ reduced Mcl-1 protein expression to induce intrinsic apoptosis in skin cancer cells." (PMID 24658058, 2014). "Our previous study indicated that Mcl-1 may play a vital role in protecting skin cancer cells against IMQ-induced apoptosis." (PMID 39272918, 2024). "Moreover, IMQ rapidly depletes the Mcl-1 protein in skin cancer cells, and Mcl-1 over-expression may result in resistance to IMQ-induced apoptosis." (PMID 24658058, 2014). "We previously reported that IMQ promptly reduced the level of the antiapoptotic Mcl-1 protein and that Mcl-1 overexpression attenuated IMQ-triggered apoptosis in skin cancer cells." (PMID 39272918, 2024).
T-cell lymphomas (4 papers, 2021 to 2025). "We pharmacologically examined the extent to which the T-cell lymphomas that emerge upon conditional loss of SMARCB1 (SNF5) are MCL-1 dependent." (PMID 41309546, 2025). "In order to determine the extent to which MCL-1 loss is a significant mechanism of action for CDK9 antagonism in the T-cell lymphomas, BH3 profiling was performed and cell lines stratified by MCL-1 dependence." (PMID 41309546, 2025). "As anticipated, MCL-1 dependent T-cell lymphomas were highly sensitive to CDK9 antagonism with AZD4573, culminating in PARP and caspase 3 cleavage within 6 h of treatment." (PMID 41309546, 2025). "The extent to which MCL-1 dependence confers sensitivity to CDK9 antagonism was examined next, as a subset of T-cell lymphomas are MCL-1 dependent." (PMID 41309546, 2025). "In summary, we have shown that CDK9 is a dependency and therapeutic vulnerability across diverse T-cell lymphoma subsets, including those that are MCL-1 dependent." (PMID 41309546, 2025). "We had previously shown that GATA-3 is oncogenic in this GEM model and demonstrate here that these T-cell lymphomas are MCL-1 independent." (PMID 41309546, 2025). "Therefore, we sought to examine the extent to which CDK9 antagonism is a therapeutic vulnerability in vivo using a GATA-3 dependent, but MCL-1 independent, T-cell lymphoma model." (PMID 41309546, 2025). "Similarly, S63845, a selective MCL-1 inhibitor, demonstrates potent anti-leukemic activity across diverse hematological malignancies, including T-cell lymphomas, where MCL-1–mediated resistance often limits the efficacy of BCL-2 antagonists." (PMID 41201565, 2025). "However, we also observed that MCL-1 independent T-cell lymphoma cells were also sensitive to both AZD4573 and an independent CDK9 antagonist [enitociclib,]." (PMID 41309546, 2025). "Dysregulation and overexpression of Mcl-1 was reported in non-Hodgkin and T-cell lymphomas." (PMID 36293331, 2022). "Consequently, CDK9 antagonism, by impairing rRNA processing, rapidly culminates in nucleolar stress, and the subsequent termination of RiBi, providing a novel MCL-1 independent mechanism by which CDK9 antagonism is a therapeutic vulnerability in GATA-3 dependent T-cell lymphomas." (PMID 41309546, 2025).
uveal melanoma (4 papers, 2012 to 2024). A melanoma derived from melanocytes of the uveal tract. "Discordin domain receptor tyrosine kinase 1 (DDR1) has also been implicated in MCL1 expression in uveal melanoma, where the downregulation of DDR1 also decreases MCL1 expression." (PMID 34831420, 2021). "We went on to examine the levels of MCL-1 and BIM expressed in several uveal melanoma cell lines following exposure to AZD8055 and selumetinib." (PMID 22808163, 2012). "Taken together, these studies demonstrate that MCL-1 downregulation is both necessary and sufficient to induce apoptosis with selumetinib, and strongly argues that MCL-1 is a singular target that is cooperatively modulated by the combination to induce apoptosis in BRAF mutant uveal melanoma." (PMID 22808163, 2012).
acute promyelocytic leukemia (3 papers, 2015 to 2024). An aggressive form of acute myeloid leukemia (AML), characterized by arrest of leukocyte differentiation at the promyelocyte stage, due to a specific chromosomal translocation t(15;17) in myeloid cells. "To test the effects of the MCL1 inhibitor S64315 on the viability of human MDSCs, we conducted in vitro tests with MDSCs isolated from 5 healthy human subjects and an acute promyelocytic leukemia cell line HL-60 (an immature MDSC model)." (PMID 38459020, 2024). "We found that propofol initiates PI3-kinase/AKT-mediated GSK-3β inactivation and Mcl-1 stabilization, rescuing the constitutive apoptosis in primary neutrophils and granulocyte-differentiated acute promyelocytic leukemia HL60 cells." (PMID 26061531, 2015). "In a previous study, sorafenib increased the treatment efficiency of acute promyelocytic leukemia (APL) by inhibiting Mcl-1." (PMID 34065991, 2021).
Cerebral ischemia (3 papers, 2013 to 2022). Restriction of arterial blood supply to the brain associated with insufficient oxygenation to support the metabolic requirements of the tissue. "In summary, the present study demonstrates the expression and cellular localization of Mcl1 in the brains of cerebral ischemia/reperfusion injury model rats." (PMID 23688351, 2013). "However, little is known about the expression profile and functions of Mcl1 in the brain following cerebral ischemia." (PMID 23688351, 2013).
chondrosarcoma (3 papers, 2018 to 2022). A malignant cartilaginous matrix-producing mesenchymal neoplasm arising from the bone and soft tissue. "Protein expression analysis of apoptotic family members Bcl-2, Bcl-xl, Bcl-w, Mcl-1, Bak and Bax revealed that Bcl-xl was highly expressed in all nine chondrosarcoma cell lines, while Bcl-2 expression was variable." (PMID 30242253, 2018). "However, to the best of our knowledge, no study has explored the effect of miRNAs that directly target anti-apoptotic molecules such as B-cell lymphoma-2 (Bcl-2), Bcl-2 lymphoma-extra large (Bcl-xL) and Myeloid cell leukemia-1 (McL-1) in chondrosarcomas." (PMID 34070455, 2021). "In the present study, using functional high-throughput miRNA screening and miRNA target prediction, we selected five miRNAs that can induce apoptosis in the SW1353 chondrosarcoma cell line by targeting BCL2, BCL2L1 or MCL1 mRNAs." (PMID 34070455, 2021). "In the three chondrosarcoma cell lines, miR-342-5p inhibited the expression of the anti-apoptotic proteins Bcl-2 and Bcl-xL, but not that of McL-1, with a more sustained effect under hypoxia." (PMID 34070455, 2021).
colon adenocarcinoma (3 papers, 2012 to 2022). "It was reported that WP1130 treatment reduces MCL-1 level in human lung and colon adenocarcinomas cell lines." (PMID 28101374, 2017). "The Mcl-1, Bcl-xL and USP9X expression patterns in human lung and colon adenocarcinomas were evaluated via immunohistochemistry." (PMID 23171055, 2012). "The colon adenocarcinoma cell line DLD-1, which expresses relatively lower Mcl-1 levels, but high Bcl-xL expression, was found to be sensitive to Bcl-xL inhibition via ABT-737." (PMID 23171055, 2012).
colorectal tumors (3 papers, 2017 to 2026). "We further support these concepts through integrative analyses of multiple transcriptomic datasets comparing normal colonic mucosa with colorectal tumors, and we discuss emerging pharmacological strategies targeting Mcl1 in colitis-associated cancer." (PMID 42194042, 2026).
gynecological cancer (3 papers, 2024). "Upregulated JOSD1 contributes to the acquisition of chemo-resistance by inhibiting mitochondrial apoptotic signaling in gynecological cancer by stabilizing MCL1." (PMID 39766302, 2024).
ischemia (3 papers, 2012 to 2018). A hypoperfusion of the BLOOD through an organ or tissue caused by a PATHOLOGIC CONSTRICTION or obstruction of its BLOOD VESSELS, or an absence of BLOOD CIRCULATION. "Expression levels of Mcl1 were detected in rats subjected to 1-hour focal ischemia followed by 4, 24 or 72 hours reperfusion." (PMID 23688351, 2013). "A smaller, alternatively spliced isoform of Mcl-1, which functions to promote apoptosis, was also found to be present in the testis upon overexposure of blots and its expression was unaffected by ischemia (data not shown)." (PMID 23216940, 2012).
ischemic stroke (3 papers, 2013 to 2025). A stroke disorder caused by obstruction of blood flow to the brain, due to thrombotic (local blood clot formation) or embolic (due to a blood clot or other material traveling from another site) event. "Further, we conducted PPI network analysis on significant genes, identifying core networks involving PARP1 for epilepsy, MCL1 for VaD, and connections between these and other proteins associated with ischemic stroke." (PMID 40624693, 2025). "In addition, our findings suggest that expression of Mcl1 is associated with the survival of neurons following ischemic stroke." (PMID 23688351, 2013). "The PPI network analysis revealed significant associations between PARP1, MCL1, and CD40, highlighting potential common pathways involved in ischemic stroke, epilepsy, and VaD." (PMID 40624693, 2025). "In addition, we examined the potential involvement of Mcl1 in ischemia-induced autophagy following ischemic stroke." (PMID 23688351, 2013). "In addition, the coexpression of Mcl1 with beclin-1 may attenuate beclin-1-dependent autophagy during ischemic stroke in rats." (PMID 23688351, 2013). "Furthermore, the interaction between MCL1 and CD40—a co-stimulatory protein involved in immune responses—indicates a link between apoptotic regulation and immune modulation in the context of ischemic stroke." (PMID 40624693, 2025). "The interaction between PARP1 and MCL1 suggests that PARP1 may regulate cell survival pathways, potentially influencing the neuroinflammatory processes observed in neurovascular diseases, including ischemic stroke and VaD." (PMID 40624693, 2025). "Interestingly, a recent study found that specific genetic deletion of neutrophils (Mcl1 knockout) did not improve neurological deficits after ischemic stroke in mice." (PMID 31927534, 2020).
large granular lymphocyte leukemia (3 papers, 2014 to 2025). "For instance, in large granular lymphocyte leukemia, targeting Stat3 with its upstream kinase JAK-selective inhibitor AG490 transcriptionally suppresses Mcl-1 and promotes apoptosis." (PMID 24529193, 2014). "Similar results were observed in large granular lymphocytic leukemia (LGLL) patient samples, where (+/−) marinopyrrole A potency was positively correlated with Mcl-1 expression: patient samples with the highest Mcl-1 protein levels produced IC50 values between 4.64 μM and 11.84 μM." (PMID 41149606, 2025).
laryngeal tumor (3 papers, 2015 to 2020). "Since it has been suggested that target gene expression analysis can be a robust indicator of functional STAT3 activation, we further evaluated the expression of ERp57 and Mcl-1 using tissue microarrays comprising 59 laryngeal tumor tissues." (PMID 25605256, 2015). "Notably, ERp57 expression strongly correlated with Mcl-1 expression in laryngeal tumor tissues, based on Spearman's correlation analysis." (PMID 25605256, 2015). "Next, we examined the expression of BCL-2, BCL-XL, and MCL-1 in TMAs comprising tissue obtained from 191 SCCHN patients at the time of surgery, from oral cavity, hypopharyngeal and laryngeal tumors." (PMID 31801952, 2019).
monocytic leukemia (3 papers, 2011 to 2025). "The investigators proved that monocytic leukemia blasts lose expression of the Venetoclax target Bcl-2 while Myeloid cell leukemia‐1 (MCL-1) protein, an antiapoptotic member of the Bcl-2 family expression is significantly higher in FAB-M5 patients." (PMID 39035053, 2024). "To explore this hypothesis, we used U-937 cells derived from a human monocytic leukaemia and expressing high levels of Mcl-1." (PMID 21750559, 2011).
ovarian tumors (3 papers, 2012 to 2025). "However, in our two PDTO models, the belinostat/AMG 176 combination displayed effective anticancer activity, supporting the concept that Mcl‐1 inhibition would represent a promising strategy to sensitize ovarian tumors to belinostat." (PMID 40483575, 2025). "USP13 and MCL1 display increased copy numbers in many TCGA (The Cancer Genome Atlas) cancer types, and are correlatively upregulated only at protein level in lung and ovarian tumor specimens." (PMID 29335437, 2018). "Third, USP13 and MCL1 were similarly amplified and overexpressed in lung and ovarian tumors." (PMID 29335437, 2018). "Similar to MCL1, USP13 is genomically amplified in a variety of human cancers and ubiquitously overexpressed in lung and ovarian tumor specimens." (PMID 29335437, 2018). "To determine whether our in vitro findings were clinically relevant in human ovarian tumors, we assessed if the ERK1/2-dependent regulation of Mcl-1 expression in CaOV3 and OVCAR3 cell lines correlated in HGSOC, the most common subtype of OC." (PMID 23158473, 2012).
pancreatic adenocarcinoma (3 papers, 2013 to 2020). "Pancreatic adenocarcinoma is another cancer that overexpresses Mcl-1." (PMID 26078955, 2015). "A previous report suggests that Mcl-1 is over-expressed in pancreatic adenocarcinoma." (PMID 24025188, 2013).
Parkinson disease (3 papers, 2014 to 2019). A progressive degenerative disorder of the central nervous system characterized by loss of dopamine producing neurons in the substantia nigra and the presence of Lewy bodies in the substantia nigra and locus coeruleus. "In addition, neurons depleted of Parkin, mutated gene in juvenile onset and familial forms of Parkinson's disease, became acutely sensitive to oxidative stress, and this was attributed to decreased MCL-1 levels." (PMID 25324720, 2014). "Such dual effects of MCL-1 may make it an attractive target for the treatment of neurodegenerative disorders such as Alzheimer's and Parkinson's disease, in which altered bioenergetics and increased neuronal loss are so prominent." (PMID 25324720, 2014). "Boosting the pro-survival function of Mcl1 should be pursued as a therapeutic approach to augment the resilience of midbrain dopaminergic neurons to apoptotic stress in Parkinson’s disease." (PMID 30479840, 2018). "Enhanced expression or functional protein activity of Mcl1 warrants a focused program of therapeutic development to attenuate dopamine neuron death in response to apoptotic stressors in Parkinson’s disease." (PMID 30479840, 2018). "Targeting the regulatory pathways controlling Mcl1 protein levels and function may therefore provide a novel therapeutic approach to strengthen dopaminergic neurons against apoptotic stress in Parkinson’s disease." (PMID 30479840, 2018).